TF (transferrin)
Diseases named in the same sentence as TF in open-access papers (continued):
Sharing a sentence is not in itself a finding about the gene and the disease.
infection (continued). "While these models do not require iron supplementation to establish Ng infection, administration of exogenous human transferrin (hTF) is essential for infection of the upper reproductive tract (URT), where availability of soluble iron is restricted." (PMID 40971931, 2025). "In contrast, transferrin is a negative acute phase reactant that down-regulates during infection, and ferritin is a positive acute phase reactant that up-regulates during infection." (PMID 40266925, 2025). "Prevalence of TF, TI, TT, antibodies to Pgp3, CT694, and Ct infection, Amhara, Ethiopia, 2019." (PMID 40067808, 2025). "Early in infection, when capsid levels are low, PRF efficiency may be higher, allowing transient TF production that could help suppress innate immune responses." (PMID 41081507, 2025). "Our results showed that after infection, one ASFV gene could inhibit TF expression directly, thereby expanding our knowledge about the interaction between the virus and the host." (PMID 38399804, 2024). "It is important to note that WT and WTR strains can infect the midgut of hematophagous insects, such as Aedes aegypti, where they encounter elevated concentrations of transferrin; this in vivo infection does not occur with the Apo strain." (PMID 39159809, 2024). "Histological analysis showed decreased TF expression in the lungs of DMF- and 4-OI-treated mice in this model compared with PBS-treated mice, demonstrating inhibition of S. aureus-driven coagulopathy via different modes of infection." (PMID 37316487, 2023). "Iron is not readily available for bacteria in the host during infection, because, as part of the nonspecific immune response, iron is bound to the iron transport molecules such as transferrin." (PMID 36932105, 2023). "In this study, we found four TF genes are upregulated at 6 h and 12 h in B488 but not in B214 after infection with P melonis." (PMID 36618646, 2022). "An important implication for TF surveillance is that our model of infection prevalence does not reflect the time course of TF itself." (PMID 33449114, 2021). "The 5 children who had infection with C. trachomatis but were seronegative were also negative for TF." (PMID 33861754, 2021). "Of the 1704 children with infection data, 21.5% of those with TF were positive for infection, and 1.6% of children without TF were positive for infection (p = 0.0010)." (PMID 33861754, 2021). "Comparing both datasets resulted in 46 TF genes that were differentially expressed as a result of DM infection as well as TSSM infestation, although not always in the same direction." (PMID 32306368, 2020). "Functional categories with the highest transcriptional changes in infection‐regulated nonsecreted proteins were the TF, TP, PK, and ROS." (PMID 32573086, 2020). "Notably, at 48 h post infection NO level was observed to be continuously increased in CSV-treated cells and 1.47-fold higher than pCold-TF-treated cells." (PMID 33553273, 2020). "While a significant number of bicluster 276 genes are up‐regulated during in vivo infection, not all of the genes are necessarily regulated by the same TF." (PMID 30833303, 2019). "Fluid-phase and transferrin uptake were not significantly enhanced during infection (compare NI and I panels), although dextran uptake was inhibited by EIPA treatment." (PMID 29727463, 2018). "Compared to Temotu, we noted that MDA did not have as significant an impact on TF prevalence in Rennell & Bellona, that there were more children there who were seropositive and that there were more children with TF who also had infection." (PMID 29588922, 2018). "In general, there has been very little or no Ct infection identified in areas where TF prevalence is below the elimination threshold." (PMID 30550537, 2018). "glabrata TF mutants (∆ada2, ∆bas1, ∆hir3, ∆ino2, ∆met31) did not activate drs expression at 24h following infection." (PMID 29535147, 2018).
infection (continued). "While reduction in the minimum duration of infection and disease episodes resulted in higher final TF prevalence levels when little or no transmission reduction was implemented." (PMID 28182664, 2017). "The exact signaling mechanism that activates transferrin expression upon pathogen infection has not been identified nor has the role of transferrin as an iron transporter been extensively studied in bloodfeeding insects." (PMID 29387018, 2017). "The sensitivity of using new pannus and TF together to diagnose Ct infection (excluding individuals presenting with new pannus without TF, or TF without new pannus) was 51.9 % and the specificity was 91.7 %." (PMID 26812948, 2016). "In order to confirm that the reduced uptake of transferrin was not due to a general defect in endocytosis due to infection, we analyzed the uptake of a lipid (MFI Bodipy) in Rab35 silenced cells." (PMID 26248231, 2015). "In the study, the TF prevalence in 0–5 year-olds in the study area was reduced below 3% after one round of treatment and Ct infection, which was at a low level initially, was not detectable in any child at 12 and 18 months of follow up." (PMID 25901349, 2015). "Six months after the baseline mass treatment, TF prevalence was 2.4% (95% CI 1.6–3.1) and no Ct infection was found in any of the 24 EAs randomised to the stopping rule." (PMID 25901349, 2015). "There was no reduction in the uptake of Alexa labeled Transferrin upon infection of wild type cells, in comparison with uninfected cells." (PMID 26248231, 2015). "Transferrin expression in larvae during experimental or natural infection with P. larvae has so far not been investigated." (PMID 25237888, 2014). "Higher levels of infection have been generally observed in individuals with TI alone (without TF) than those with TF, and we observed this same trend, though we had few TI cases in our sample." (PMID 24722392, 2014). "Decrease in PHD activity due to LD-infection was reversed by supplementation of only holo-transferrin but not by apo-transferrin." (PMID 22701652, 2012). "The corresponding flower tissues showed marked reductions in the levels of SCL6 (10 folds) and NAM (3 folds) while CBF TF expression was not altered in ToLCNDV infection." (PMID 20973960, 2010). "However, siRNA knockdown of CME components in RD cells inhibited the cellular uptake of transferrin, yet had no significant impact on EV-D68 infection." (PMID 42037410, 2026). "However, the differences in the magnitude of the near-complete block in infection as opposed to the minor reduction in transferrin accumulation led us to conclude that the main effect of NH4Cl reflects the requirement of endosomal pH for viral processing." (PMID 39981379, 2025). "We speculate that the functional consequence of this suppression is not to completely abolish TF expression, but rather to modulate it over the course of infection." (PMID 41081507, 2025). "Interestingly, KP infected cells treated with TF showed increased intracellular pathogen numbers compared to not TF supplemented cells after 24 h of infection." (PMID 37637102, 2023). "PCR positivity in the absence of TF or seropositivity was more common in younger children, possibly reflecting individuals with early infections who did not yet have inflammatory sequalae resulting in clinical signs and without an exposure level sufficient for seroconversion." (PMID 35439248, 2022). "The most likely explanation, however, for the high prevalence of TF in the absence of TT in these populations is that a proportion of TF in Melanesia is follicular inflammation triggered by something other than CT infection, with the “trachomatous” part of the sign’s name being misleading." (PMID 31965155, 2021). "Of the 5 with infection who were seronegative, none had TF either." (PMID 33861754, 2021).
infection (continued). "Similarly, levels of Transferrin, Afamin, Fetuin A (Alpha-2-HS Glycoprotein), Fetuin B and Transthyretin were reduced in both infection types, and no statistical difference was found between their levels." (PMID 30774579, 2019). "Furthermore, years after MDA has been administered, TF persists at levels above the threshold for elimination (> 5%) in communities where Ct infection is not readily detectable." (PMID 29410954, 2017). "So-called negative acute phase proteins like transferrin, α-2-HS-glycoprotein, fibronectin and pre-albumin were consistently reduced in malnourished children, even without infections." (PMID 25153531, 2014). "Here we have investigated the involvement of the clathrin pathway in BTV-1 entry and infection of BHK cells using deletion mutants of AP180 (AP180C) and Eps15 (Eps15-Ed95/295; from here known as DN-Esp15) which act as DN inhibitors of CME and block uptake of transferrin." (PMID 20613878, 2010). "The fact that PRRSV expresses multiple versions of PLP2 through the nsp2TF products, which each may have particular functions that may play critical roles in the infection, makes mutation of the PLP2 sequence more impactful than in viruses that do not express these extra TF products such as EAV." (PMID 38096325, 2023). "Transferrin fluctuation further indicates systemic involvement, while the lack of significant changes in other proteins such as haptoglobin or α1-antitrypsin may reflect the nonestablishment of an acute infection or the early timing of sample collection relative to peak response." (PMID 40951670, 2025). "We found that the ability of CagA to increase internalized transferrin depends on the presence of the EPIYA motifs, as infection of polarized monolayers with a mutant lacking these phosphorylation domains resembled ΔcagA infection." (PMID 21589900, 2011). "We stress that KCTD12, TF, LTF, and MPO are host-response proteins; their altered serum-exosomal levels mirror the child’s innate reaction to infection with azithromycin-resistant M. pneumoniae and do not reflect or cause the bacterial mutation that directly confers resistance." (PMID 41451080, 2025). "Induction of metal acquisition genes in the Gc_1h condition may be explained by the lack of accessible iron for Gc in the infection medium (RPMI+10% FBS), as Gc TbpAB can only use human transferrin, not bovine." (PMID 38976720, 2024). "In contrast to NM larvae, and in the absence of infection, the M cuticle has higher basal levels of specific antifungal factors (apolipophorin III, gallerimycin, IMPI), antibacterial factors (gloverin) and general defenses (DOPA-decarboxylase, transferrin)." (PMID 31724467, 2019). "Thus, a single round of MDA reduced TF to low levels, and there were no apparent benefits to two further rounds of mass treatment, relative to discontinuing MDA post-baseline based on tests for infection." (PMID 25901349, 2015).
bacterial infection (32 papers, 2006 to 2025). "We tested effects of microbial products from both pathogenic and probiotic bacteria on transferrin expression in human primary macrophages and mouse normal embryonic liver cell line (BNL CL.2) to investigate the association of transferrin with bacterial infection and/or commensalism." (PMID 38274126, 2024). "Transferrin is also known to be an antibiotic agent in insects which may reduce the risk of bacterial infections during the cold winter." (PMID 32038298, 2019). "To further dissect the regulatory difference induced by bacterial infection, we conducted the differential TF expression and SCENIC analysis to compare the TF expression and regulon activities in each neutrophil subpopulation." (PMID 36269754, 2022). "Humans utilize nutritional immunity to limit bacterial infections, employing metalloproteins such as hemoglobin, transferrin, and lactoferrin across a variety of physiological niches to sequester iron from invading bacteria." (PMID 36189345, 2022). "Apart from active iron uptake by small intestine enterocytes, the host can also produce high affinity iron-sequestering proteins such as lactoferrin and transferrin, which serves as a primary innate mechanism to limit some bacterial infections." (PMID 33062434, 2020). "Transferrin expression is induced in flies that house bacterial infections but suppressed in the midgut of T. brucei infected tsetse and in baculovirus infected Spodoptera littoralis." (PMID 29155830, 2017). "The Major royal jelly protein has antimicrobial properties is expressed in response to bacterial infection in honeybees, while Transferrin plays an important role in the immune system of insects and vertebrates." (PMID 29155830, 2017). "In summary, transferrin has been identified as an important regulator of iron homeostasis during blood digestion, larval and pupal development and bacterial infection in arthropods." (PMID 29387018, 2017). "Upon bacterial infection, TF and TFR can create a bacteriostatic environment by reducing the availability of iron to pathogens for proliferation." (PMID 27898025, 2016). "One immediate host response to bacterial infection is to further decrease the amount of available iron, so that the level of saturation of transferrin drops to less than 5%." (PMID 23209633, 2012). "The conserved dual functions of transferrin in the iron metabolism and immune response were recently demonstrated in sea bass, which responded to both bacterial infection and altered iron status by modulating the liver and brain expression of transferrin." (PMID 21612617, 2011). "A recent study in fish showed a reduction in serum iron and saturated transferrin following a bacterial infection." (PMID 21206752, 2010). "Interestingly, SP140 which is an important negative regulator of Type I IFN and an essential transcriptional regulator for resistance to bacterial infections, was one of the most significant predicted TF for the downregulated genes." (PMID 40762982, 2025). "In the present study, our results showed that the expression of TF in termites changed significantly after bacterial infection, and five insect TF genes were found to be downregulated (1.9–12.7-fold), while one gene was upregulated (23.31-fold), in O. formosanus following S. marcescens infection." (PMID 32985611, 2020). "Moreover, the transferrin gene has been identified in several fish species, including the Japanese medaka, and is known to be induced at the transcriptional level upon bacterial infection stress." (PMID 32256492, 2020). "In addition, a trend toward upregulation of transferrin expression was observed at 9–24 h post-bacterial infection." (PMID 31836758, 2019). "As the endometrial immune system is constantly challenged by bacteria ascending through the cervix, transferrin and galectins-1 might contribute to the protection of the endometrium against bacterial infection." (PMID 21791079, 2011).
bacterial infection (continued). "By limiting the availability of iron for replicating pathogens transferrin provides resistance to bacterial infections, but an iron-independent role of transferrin in the immune system is evidenced by the involvement of transferrin and its receptor in early T cell differentiation in the thymus." (PMID 21612617, 2011). "Iron is a key limiting reagent during in vivo bacterial infection, and multiple systems have been identified in SA for binding and scavenging iron from mammalian host iron-binding proteins (IBPs) such as lactoferrin, transferrin and hemoglobin." (PMID 17971880, 2007). "This may also explain the higher frequency of SNPs in the coding region of the transferrin gene, which plays an important role in resistance to bacterial infection in a variety of organisms and was earlier reported to be under positive selection in S. salar." (PMID 16872523, 2006). "In particular, we demonstrated that miR-375 targets TF and TFR and could thus be involved in iron homeostasis, especially during bacterial infection." (PMID 27898025, 2016). "Taken with the lack of transferrin regulation observed in our study, which contradicts past work reporting up-regulation of transferrin by AS, it is possible that the transferrin system responds to bacterial infection with a complex temporal dynamic that was not captured by our study." (PMID 30285610, 2018).
cardiovascular disease (23 papers, 2012 to 2024). "Similar change in ceroplasmin and transferrin levels have previously been linked to oxidative stress and decreased NO bioavailability, and associated with cardiovascular disease risk in clinical studies." (PMID 36681048, 2023). "Elevated serum FTN concentration, along with high levels of free iron and transferrin saturation, has been linked to an increased risk of cardiovascular disease in humans." (PMID 37791060, 2023). "Moreover, high ferritin levels and low transferrin saturation has been reported to be associated with an increased risk of cardiovascular disease." (PMID 38324145, 2024). "Detailed examination of the regulation and correlation patterns suggests that the regulatory activities of the two TF genes could have high clinical and interventional impacts on retarding and preventing carotid atherosclerosis and cardiovascular diseases." (PMID 38397203, 2024). "Although VF is a relatively small fat depot (in this study it comprised only 1.4% of body weight and 3% of TF), but due to its high lipolytic activity and ability to release inflammatory cytokines, it has been found to be a robust predictor of cardiovascular disease." (PMID 32892317, 2021). "By adding a further piece of evidence in understanding the mechanisms of TF expression in monocytes, which are key cells in the atherothrombotic process, our results provide further support to the rationale for an effective ApoCIII-lowering therapy in cardiovascular diseases." (PMID 36768547, 2023). "Cardiovascular diseases are also accompanied by the reduction of negative acute phase reactants such as albumin, transferrin, transthyretin, retinol-binding protein, antithrombin, and transcortin." (PMID 24049653, 2012). "Cardiovascular disease is also accompanied by the reduction of negative acute phase reactants such as albumin, transferrin, transthyretin, retinol-binding protein, antithrombin, and transcortin." (PMID 24049653, 2012).